Y_RNA (Y RNA )
Gene: Miscellaneous RNA gene on chromosome 4 (119,947,131 to 119,947,232, forward strand). Ensembl gene ENSG00000200553.
Homologues: Orthologues: chimpanzee Y_RNA (99% identical), macaque Y_RNA (92% identical), dog Y_RNA (81% identical), tropical clawed frog Y_RNA (75% identical). Paralogues in human: RNY3 (88% identical), Y_RNA (87% identical), Y_RNA (86% identical), RNY3P1 (85% identical), Y_RNA (85% identical), Y_RNA (84% identical), Y_RNA (83% identical), RNY3P11 (82% identical), RNY3P14 (82% identical), RNY3P16 (82% identical), Y_RNA (82% identical), Y_RNA (81% identical), and 95 more.